IL6 (interleukin 6)
Diseases named in the same sentence as IL6 in open-access papers (continued):
Sharing a sentence is not in itself a finding about the gene and the disease.
viral infection (continued). "A detailed understanding of the biology of IL-6, the IL-6R receptor and its signalling axis can bring new information essential for the amelioration of the problems of ageing and offer an efficient therapy for malignancies and viral infections." (PMID 33114676, 2020). "Upregulation of IL-6 during certain viral infections may promote virus survival and/or exacerbation of clinical disease." (PMID 33224264, 2020). "When macrophages and DCs fail to galvanize and educate T-cell and B-cell activation, they continue to aberrantly secrete cytokines such as IL-6 and TNFα in efforts to control viral infection, however this results in cascading inflammation, eventually resulting in cytokine storm." (PMID 32760409, 2020). "IL-6 stimulates inflammation, under the action of variable stimuli, such as allogenic and bacterial cells, immune complexes, LPS, reactive oxygen species, malignant cells, and viral infections." (PMID 32708120, 2020). "These latter findings support the hypothesis that IL-6 upregulation during viral infections may promote virus survival and the exacerbation of the clinical disease." (PMID 32354030, 2020). "However, IL-6 has also been shown to be an important mediator of innate immunity and important for the host recovery from acute viral infection." (PMID 33071786, 2020). "It is also possible that IL-6 may act on other sites not blocked by α-IL-6R mAb, and that this may yield a potential advantage of using α-IL-6 mAb to treat CRS brought about by a viral infection." (PMID 33071786, 2020). "Empirical studies support the important role of IL-6 during viral infections but numerous reports also propose that the up-regulation of IL-6 expression may have negative consequences for the cellular immune response against viruses." (PMID 32788852, 2020). "During viral infections, iron homeostasis is perturbed, leading to iron disorders which are worsened by the action of pro-inflammatory cytokines, including interleukin-6 (IL-6)." (PMID 32664543, 2020). "However, IL-6 has also been shown to be an important mediator of innate immunity and important for the host response to an acute viral infection." (PMID 33071786, 2020). "In particular we observed that knockout of Pellino-1 in the murine lung resulted in increased production of proinflammatory cytokines IL-6 and TNFα upon viral infection, accompanied by enhanced recruitment of immune cells to the airways, without any change in viral replication." (PMID 32984077, 2020). "Interestingly, the combination of Cs and viral infection in our model augmented the levels of IL-6 in serum which was inhibited by Ladarixin, protecting mice from a severe systemic inflammatory condition." (PMID 33123138, 2020). "Interestingly, virus infection can lead to an induction of the inflammation process, characterized by excessive production of nitric oxide (NO), Interleukin-1 (IL-1), Interleukin-6 (IL-6) and Tumor Necrosis Factor-α (TNF-α)." (PMID 32825564, 2020). "Comparison of IL-6′s role in viral infections versus CRS after CAR-T cell infusion is informative." (PMID 33051534, 2020). "The associations between SARS-CoV-2 viral load with levels of CRP and IL-6 results also indicate that active viral infection could contribute to the hyperinflammatory state that is a hallmark of severe COVID-1925." (PMID 33127906, 2020). "In addition to allowing efficient BV transduction, wtBV has been shown to immunostimulate the release of inflammatory cytokines, including INFs, TNF-α, IL1A, IL1B and IL6 in mammalian cells and confer protection from lethal virus infection in mice." (PMID 31649751, 2019). "Taken together, these results reveal that SOCS3 might play a crucial role not only in suppressing IL-6/STAT3 signaling but also in feedback regulation of IL-6 expression during the viral infection." (PMID 31474976, 2019).
viral infection (continued). "The antagonism between STAT1 and STAT3 seems to be cell type-specific or specific to a certain gene locus, as a cooperation between STAT1 and STAT3 downstream of IL-6 has been described for optimal Bcl6 induction and Tfh differentiation in response to viral infections." (PMID 31998303, 2019). "In addition, C188-9 treatment decreased virus yield in NDV/FMW-infected cells compared to virus infection alone whereas IL-6 treatment increased virus titers in A375 cells at 48 hpi and in C8161 cells at 24 hpi." (PMID 31192135, 2019). "Indeed, high serum levels of IL-6 have been correlated with disease severity and mortality in cases of bacterial sepsis and viral infections, such as E71 and Sindbis virus infections." (PMID 31675371, 2019). "Since the proinflammatory response of DCs might contribute to antiviral immunity against LACV, we performed cytokine ELISA for hallmark cytokines of proinflammatory responses, namely, TNF-α and IL-6 after 8h and 24h of virus infection." (PMID 30917612, 2019). "These latter findings lend support to the hypothesis that upregulation of IL-6 during certain viral infections may promote virus survival and/or exacerbation of clinical disease." (PMID 31134045, 2019). "Other reports have also emphasized the importance of IL-6 during virus infections." (PMID 31134045, 2019). "Additional work exploring the potential therapeutic use of blocking IL-6 or different products affected by its activity might provide insight into controlling persistent viral infections." (PMID 31134045, 2019). "Although Parkin deficiency does not affect viral induced expression of IL-6 in cell infection studies, it is interesting to note from our earlier data that Park2−/− mice show augmented lung levels of IL-6 in response to viral infection." (PMID 31229895, 2019). "HCC patients with virus infection have been shown to have high expression of IL-6." (PMID 31771617, 2019). "Procalcitonin has been found to have better specificity, sensitivity, predictive value and likelihood ratio than CRP, interleukin 6 and interferon-alpha in children for distinguishing between bacterial and viral infections in other studies from various parts of the world." (PMID 30388962, 2018). "Moreover, IFAN1 and IL-6 mRNA were significantly upregulated by viral infection, indicating activation of interferon response and inflammatory process." (PMID 30053898, 2018). "To test whether IL-6 exposure affects viral infection, we initially quantified the effect of IL-6 on NS3 levels in EHDV-TAU-infected LNCaP and LNCaP-JAK1 cells." (PMID 29441069, 2018). "It has been speculated that elevated IFNs, TNF-α, and IL-6 during viral infection correlated with the severity and outcome of viral diseases." (PMID 30016363, 2018). "IL‐6 expression can be induced as a defensive mechanism against viral infection." (PMID 28865178, 2018). "FDC are responsible for the production of IL-6 at this late phase of viral infection." (PMID 30405612, 2018). "Notably, co-infections led to a significant increase in the levels of TNF-α and IL-6, cytokines that are widely considered to play a crucial role in the early pathogenesis of both viral diseases." (PMID 28644900, 2017). "They had a prominent systemic immune response involving IL-6, TNF-α, and MCP-1 which may be due to the activation of macrophages that was caused by the viral infection." (PMID 28352642, 2017). "The pro-inflammatory cytokine IL-6 is a dominant regulator of hepatic hepcidin production in bacterial infections and other inflammatory conditions, but IL-6 concentrations are often only mildly elevated in viral infections." (PMID 29258550, 2017). "The miR-US5-1/miR-UL112-3p mutant virus infection resulted in increased secretion of IL-6, CCL5, and TNF-α (in THP-1 cells) compared to WT-infected cells, which was significantly reduced in cells infected with the miRNA mutant virus expressing shRNAs targeting IKKα and IKKβ." (PMID 28270578, 2017).
viral infection (continued). "Poly-ICLC is one TLR3 agonist which is often combined with vaccine and cellular immunotherapies in order to induce type I interferons and mimic inflammatory response to systemic viral infection by amplification of interferons alpha and gamma as well as IL-1a and IL-6." (PMID 29157306, 2017). "However, the model of viral infection provides context for indirect evidence of increased IL-6 expression consequent to IFN-α priming." (PMID 28289923, 2017). "Virus infection through TLR interaction induces cytokines including Il-6 and Il-8." (PMID 28187208, 2017). "The secretion of procalcitonin during these bacterial infections is stimulated by cytokine plasma markers such as IL-6 and tumor necrosis factor-α, whereas viral infections commonly attenuate the procalcitonin response, likely due to increased IFN-γ production." (PMID 27977798, 2016). "IL-6 plays an important role in immune responses against bacterial and viral infection." (PMID 27240351, 2016). "Thus, the IL-18 response in viral infections is responsible for hyperferritinemia, while bacterial infections are characterized by an IL-1β/IL-6 response, culminating in elevated plasma levels of CRP." (PMID 27977798, 2016). "IRF5 knockout mice were reported to be susceptible to viral infections, while, the expression levels of type I IFNs and other pro-inflammatory cytokines including tumour-necrosis factor (TNF)-α, interleukin (IL)-6 and IL-12, were reduced in response to viral infections." (PMID 27350041, 2016). "Expression of both CASP1 and IL6 genes could be induced not only by viral infection directly but also by GPR160 siRNAs in a virus-free transient transfection system." (PMID 26871479, 2016). "Further studies are necessary to clarify which BM cells produce IL-27 during malaria infection; mesenchymal stromal cells might be a candidate because of their reported IL-6 production during viral infection, as described in the next section." (PMID 26991425, 2016). "IL-6 is extremely inducible in response to IL-1, TNFα, viral infection and angiotensin II peptide." (PMID 27884156, 2016). "However, in BEAS-2B cells, continuous presence of P. aeruginosa during viral infection was required to observe a sustained synergistic effect on IL-6 release." (PMID 27259950, 2016). "Thereafter, we also asked whether the miR-136 would contribute to IL-6 mRNA suppression during virus infection." (PMID 26450567, 2015). "Given the characteristic time-space clustering and the expression of proinflammatory and profibrotic cytokines both in the liver and in the circulation, including interleukin-6 (IL-6) and interleukin-8 (IL-8), isolated BA is believed by some to be secondary to hepatobiliary viral infection." (PMID 26247025, 2015). "Wild-type MAVS could only induce IL-6 expression in response to Sendai virus infection, while MAVS (Δaa-141–160/Δaa-201–350/Δaa-401–450) induced IL-6 expression independently of virus infection." (PMID 26183716, 2015). "The induction of IL-6, mediated by IL-32, is crucial for the host response against viral infection." (PMID 26087456, 2015). "In contrast, other studies suggested that viral infection induced vigorous IL-6 production may promote the disease development." (PMID 25994622, 2015). "When available, comparison of assays measuring IFN-γ, IL-10, and IL-6 may be useful for distinguishing between bacterial sepsis, viral infections, and HLH in febrile patients." (PMID 26347828, 2015). "In all 11 invasive viral infections there was a significant increase of IL-6 (P = 0.0008)." (PMID 26315105, 2015). "Thus, our result adds evidence to the counter-regulative properties of TLR-induced IL-6 on inducing acquired immunity in viral infections." (PMID 25994622, 2015). "Interestingly, SeV- or HSV-1-induced expression of the proinflammatory cytokines TNFα and IL-6 was inhibited by RNF26 knockdown at all examined time points after viral infection." (PMID 25254379, 2014).
viral infection (continued). "Moreover, it can also decrease the expression level of the inflammatory cytokine IL-6 during viral infection." (PMID 24795704, 2014). "Interestingly, the expression of IL-6 was decreased in cardiomyocytes 6 hours after viral infection." (PMID 25374444, 2014). "NF-κB signaling, which regulates a number of inflammatory genes, including iNOS, COX-2, TNF-α, IL-1β, and IL-6, can be stimulated by pathological stimuli, such as viral infection, UV radiation, and free radicals, and its dysregulation is involved in the pathogenesis of many inflammatory disorders." (PMID 24475143, 2014). "The observed exercise-induced inhibition of IL-6, coupled with an enhanced anti-inflammatory cytokine response, may therefore be indicative of somewhat compromised host-defence to viral infection." (PMID 24967270, 2014). "In this study, the expression levels of the majority of genes involved in the TNF signaling pathway, including those encoding TNF, IL-6, CCL20, caspase 10, caspase 3, NF-κB, and TGF-β-activated kinase 1 (TAK1), were significantly downregulated after viral infection." (PMID 25423176, 2014). "BMDCs produce pro-inflammatory cytokines including TNFα and IL6 upon viral infection." (PMID 23936008, 2013). "Analysis of cytokines induction in infected human alveolar epithelial cells with the M and F viruses as well as the seasonal A/New/Caledonia/20/99 (NC) strain revealed that F virus infection induces earlier and higher levels of IL-6, IL-8, MCP-1, GM-CSF and RANTES than M or NC infections." (PMID 23326447, 2013). "Similarly, RS viral infection induces the release of IL-1β, IL-6, and IL-8 from human airway and alveolar epithelial cells." (PMID 22966430, 2012). "Our data showed SD/09 viral infection induced high levels of IL-6 in mouse lung, which may also play an important role in the course of ARDS." (PMID 22235288, 2012). "The generation of polarized Th-17 cells during viral infection has been correlated with high levels of IL-6 and may also be influenced by transforming growth factor-β (TGF-β)." (PMID 23071829, 2012). "Viral infections also enhance the production of inflammatory mediators and substances in airway epithelial cells, mast cells, and other inflammatory cells, such as IL-1, IL-6, IL-8, GM-CSF, RANTES, histamine, and intercellular adhesion molecule-1." (PMID 22966430, 2012). "In addition, viral infection led to production of detectable levels of the pro-inflammatory cytokine IL-6, with a trend for being slightly increased in lung tissue from PAD4 KO mice, though not reaching statistical significance." (PMID 21779371, 2011). "Indeed, type I IFNs and IL-6 have been shown to be required in the control of viral infections, and type I IFNs play a role in the generation of effector and memory CD8+ T cells." (PMID 21423804, 2011). "The early inflammatory response and chronic disease severity was controlled by supplementing the viral infection with recombinant IL-6 indicating that IL-6 functions as a regulator of the early host response and has a protective role during the progression of CB3-induced chronic myocarditis." (PMID 19587788, 2009). "Our results suggest a regulatory role for IL-6 following viral infection." (PMID 19587788, 2009). "Moreover, increased bacterial adhesion may be mediated not only by virus infection but also by pro-inflammatory cytokines such as IL-6, IL-1α, and TNF-α, which upregulate receptors like ICAM-1, PAFr, and CEACAM1." (PMID 40520162, 2025). "Similarly, viral infection also induces the expression of several pro-inflammatory cytokines, including interleukin 6 (IL–6), interleukin 10 (IL–10), interferon β(IFN–β), and tumor necrosis factor α (TNF–α), all of which are significantly increased at the protein level." (PMID 39941149, 2025).
viral infection (continued). "Due to the reversible nature of targeting metabolic enzymes with small molecule inhibitors, targeting the metabolic enzymes induced by IL-6 can be used to fine tune inflammation associated with autoimmune disease or viral infection without causing deleterious effects on protective immunity." (PMID 40936905, 2025). "Likewise, alterations in WBC counts and inflammatory markers such as C-reactive protein (CRP) and interleukin-6 (IL-6) reflect the systemic inflammatory response to viral infection and may serve as prognostic indicators of disease severity and progression." (PMID 39087175, 2024). "However, our previous laboratory study found that insulin treatment might significantly worsen viral infections by elevating interleukin-6 levels and the ratio of severe complications to death." (PMID 38755442, 2024). "Indeed, while some studies emphasize the role of IL-6 in mounting an effective immune response against certain viruses, others suggest that its elevation during specific viral infections could potentially facilitate virus survival or worsen clinical outcomes." (PMID 39066228, 2024). "Some papers propose that this may be due to a different expression of angiotensin-converting enzyme 2 (ACE-2) or transmembrane protease serine 2 (TMPRSS2) receptors, or to lower production of proinflammatory cytokines such as interleukin-6 (IL-6) in women after a viral infection." (PMID 39036098, 2024). "Viral infection results in the activation of several pattern-recognition receptors (PRRs) and toll-like receptors (TLRs), leading to the activation of NF-κB, a transcription factor that promotes the expression of pro-inflammatory cytokines such as interleukin 6 (IL-6) and interleukin 1β (IL-1β)." (PMID 38474248, 2024). "The role of IL-6 during viral infections may be protective, by inhibiting virus replication or deleterious, through a synergistic interaction with IL-17 that induces antiapoptotic molecules avoiding elimination of infected cells and promoting long-term infections." (PMID 39296294, 2024). "Thus, we postulated that IL6/STAT3 signaling might regulate HSP90 expression to engage in viral infection." (PMID 37099596, 2023). "Thus, the interaction between virus and host cells via IL-17 and IL-6 and/or other cytokines results in persistent viral infection and prolonged harmful immune responses including various autoimmune responses, which ultimately lead to the development of TMEV-induced demyelinating disease." (PMID 37153539, 2023). "Furthermore, the increased IL-6 production in the control group could enhance the generation of IL-17-producing Th17 cells, as evidence supports a linkage between IL-17 and IL-6-mediated activity in viral infections." (PMID 38283346, 2023). "Interestingly, IL6/STAT3 signaling is a unique and highly pleiotropic pathway that is evolutionarily conserved and is implicated in both temperature-induced immune responses and virus infection." (PMID 37099596, 2023). "Nevertheless, our work provides further credence to the pivotal roles of IL6 and HSP90 as risk factors of susceptibility to viral infection, highlighting the feasibility and rationality of developing targeted preventives towards IL6-STAT3 signaling and HSP90 for viral diseases in the future." (PMID 37099596, 2023). "Thus, the differences in the type and intensity of TLR signals on antigen-presenting cells may affect the levels of viral infection, replication, and production of IL-1β and IL-6, which are critical factors in the development of demyelinating disease." (PMID 37153539, 2023). "Finally, we found a positive regulation of genes related to immune response to virus infections (Type I Interferons, inflammatory cytokines (IL-6, TNF and NF-κB), NLRP3 inflammasome, anti-inflammatory cytokines (IL-10), and cell death pathways (pyroptosis and apoptosis)) in RA individuals." (PMID 37628893, 2023).